RN7SL673P (RNA, 7SL, cytoplasmic 673, pseudogene)
Gene: Miscellaneous RNA gene on chromosome 15 (30,091,662 to 30,091,898, forward strand). Ensembl gene ENSG00000273818.
Homologues: Orthologues: chimpanzee Metazoa_SRP (100% identical), pig Metazoa_SRP (59% identical). Paralogues in human: RN7SL469P (100% identical), RN7SL628P (99% identical), RN7SL719P (99% identical), RN7SL82P (99% identical), RN7SL495P (99% identical), RN7SL185P (98% identical), RN7SL196P (97% identical), RN7SL286P (97% identical), RN7SL539P (97% identical), RN7SL796P (97% identical), Metazoa_SRP (92% identical), RN7SL106P (92% identical), and 709 more.